GFRAL (GDNF family receptor alpha like)
Diseases named in the same sentence as GFRAL in open-access papers (continued):
Sharing a sentence is not in itself a finding about the gene and the disease.
pancreatic cancer (6 papers, 2020 to 2024). "Stage IV pancreatic cancer tissues showed even higher levels of GFRAL expression than stage I. In addition, Kaplan–Meier analysis has shown that higher levels of GFRAL expression are associated with lower 5-year overall survival rates in patients." (PMID 38335385, 2024). "However, the direct association between GDF-15 and GFRAL was only demonstrated in pancreatic cancer." (PMID 39000420, 2024). "GFRAL was initially thought to be expressed exclusively in brain tissues; however, some subsequent studies revealed that it is also expressed in pancreatic cancer cells, prostate cancer cells, and vascular endothelial cells." (PMID 38254638, 2023). "After overexpression GFRAL in pancreatic cancer cells, the effect of GDF-15 was significantly enhanced." (PMID 33201838, 2020). "The newly identified GDF-15/GFRAL axis provides a vital and novel potential biomarker for diagnosis and therapeutics in pancreatic cancer." (PMID 33201838, 2020). "Overall, these results suggest that the tumor-promoting effects of GDF-15 in pancreatic cancer are mediated by the GDF-15/GFRAL pathway." (PMID 33201838, 2020). "On average, GFRAL expression was higher in stage IV pancreatic cancer tissues compared with that in stage I tissues." (PMID 33201838, 2020). "The results indicated that GFRAL expression was observably upregulated in pancreatic cancer tissues compared with that in normal pancreatic tissues." (PMID 33201838, 2020). "Cell proliferation assays showed that GFRAL overexpression significantly enhanced pancreatic cancer cell proliferation after coculture with 0ng/ml, 10ng/ml or 20ng/ml GDF-15 protein." (PMID 33201838, 2020). "GFRAL protein expression was detected in 117 pancreatic cancer tissues and 13 normal pancreatic tissues using immunohistochemistry." (PMID 33201838, 2020). "GFRAL was mostly expressed on the cell membrane and the positive expression rate of GFRAL in pancreatic cancer tissues was about 94%." (PMID 33201838, 2020). "Our findings, together with previous evidence, indicate that GDF-15/GFRAL axis can promote pancreatic cancer proliferation and migration." (PMID 33201838, 2020). "Therefore, we performed immunohistochemistry and detected that GFRAL was upregulated in human pancreatic cancer tissues." (PMID 33201838, 2020). "Finally, we analyzed the correlation between GDF-15 and GFRAL in 13 pairs of pancreatic cancer blood and tissues." (PMID 33201838, 2020). "However, whether and how GFRAL is involved in the pathogenesis of pancreatic cancer is yet to be investigated." (PMID 33201838, 2020). "In the NCT04068896 phase 1/2 dose-finding study with a GFRAL antagonist monoclonal antibody in combination therapy, blocking of GFD-15 signaling is evaluated in subjects with advanced solid tumors and pancreatic cancer." (PMID 36361969, 2022). "The data suggested that compared with the normal pancreatic ductal epithelial cell line HPDE, GFRAL was upregulated in pancreatic cancer lines AsPC-1, BxPC-3, CFPAC-1, SW1990, but not Panc-1 or Hs766t." (PMID 33201838, 2020). "To explore whether GDF-15 plays a biological role in pancreatic cancer tissues by means of GFRAL, we performed dual immunofluorescence staining assay to detect the localization of GDF-15 and GFRAL, and found that both protein molecules are co-expressed in pancreatic ductal epithelial cancer cells." (PMID 33201838, 2020). "So far, there is no related study describing the function of GFRAL in pancreatic cancer." (PMID 33201838, 2020).
gastric cancer (4 papers, 2021 to 2025). A primary or metastatic malignant neoplasm involving the stomach. "While GFRAL receptor antagonists alleviate cachexia, appetite loss, and nausea, aberrant GFRAL expression has been reported in pancreatic and gastric cancer cells." (PMID 41294666, 2025). "Conversely, GDF-15 overproduction by gastric cancer cells mediates GFRAL signalling in tumour cells, resulting in cisplatin resistance." (PMID 41294666, 2025). "Our results in mice were confirmed with the detection of GFRAL-IR in human normal gastric mucosa as well as in gastric cancer cells." (PMID 38474863, 2024). "The knowledge about the role of GDF15 and its signaling through a GFRAL/RET-dependent complex in gastric cancer is only beginning to be recognized, similar as in other human cancers." (PMID 34149933, 2021). "In our cohort, a very similar rate of GFRAL positivity in the intestinal-type and mixed-type gastric carcinomas is probably related to the fact that our mixed-type cases are characterized by a predominance of intestinal histological component (mixed-predominantly intestinal type)." (PMID 34149933, 2021). "Although it has been initially hypothesized that GFRAL expression was restricted to the central nervous system, more recent studies report the presence of GFRAL in peripheral tissues, such as adipose, pancreatic ductal adenocarcinoma, and gastric cancer tissue." (PMID 41287825, 2025). "Furthermore, the correlation analysis between the expression status of GFRAL and clinicopathological characteristics of GC patients showed a markedly lower GFRAL expression level in poorly differentiated gastric cancer cells compared to those with more differentiated histology." (PMID 34149933, 2021).
prostate carcinoma (4 papers, 2019 to 2024). A carcinoma that arises from epithelial cells of the prostate gland. "GFRAL/RET expression was also shown in osteoblasts in a murine model of prostate cancer bone metastasis." (PMID 39000420, 2024). "The Phase I/II study is currently evaluating NGM120, a GFRAL antagonist antibody, on cachexia in participants with advanced pancreatic and prostate cancer." (PMID 39000420, 2024). "Recent data showed that GFRAL expression is also present in human adipocytes and prostate cancer cells." (PMID 34975851, 2021).
anorexia nervosa (3 papers, 2022 to 2024). A disorder most often seen in adolescent females characterized by a refusal to maintain a minimally normal body weight, an intense fear of gaining weight, a disturbance in body image, and, in postmenarcheal females, the development of amenorrhea. "Interestingly, a gene variant of GFRAL was found using next-generation sequencing in a cohort of patients exhibiting diverse clinical signs of anorexia nervosa; however, its clinical relevance is unknown." (PMID 38474863, 2024).
breast carcinoma (3 papers, 2017 to 2022). "GFRAL has been proposed as a drug target for appetite-related disorders, and similarly may provide a future therapeutic strategy in breast cancer." (PMID 31861872, 2019). "Thus, future evaluation of the role of GFRAL and associated signaling pathways in EMT and invasion of GDF15-overexpressing breast cancer cells is warranted." (PMID 29212236, 2017).
melanoma (3 papers, 2023 to 2025). A malignant, usually aggressive tumor composed of atypical, neoplastic melanocytes. "Furthermore, pharmacological blockade of the GDF‐15/GFRAL axis using a GFRAL antagonist antibody effectively mitigated anorexia and muscle wasting in a melanoma mouse model treated with cisplatin." (PMID 40343378, 2025).
Anxiety (2 papers, 2022 to 2025). Intense feelings of nervousness, tension, or panic often arise in response to interpersonal stresses. "Muscle mitochondrial stress signals to the brain via hindbrain-specific GFRAL receptor signaling to promote hypothalamic CRH induction, which associates with GFRAL-dependent modulation of systemic energy metabolism, diurnal food intake, and anxiety-like behavior." (PMID 36271504, 2022). "Here, we report that muscle mitochondrial stress signals to the brain via GFRAL receptor signaling to promote hypothalamic Crh induction in both male and female TG mice, which associates with GFRAL-dependent modulation of systemic energy metabolism, diurnal food intake, and anxiety-like behavior." (PMID 36271504, 2022). "GDF15 emerges as a key stress-responsive biomarker that links peripheral metabolism with brainstem GDNF family receptor alpha-like (GFRAL)-mediated anxiety circuits." (PMID 40806735, 2025). "Altogether, these data show a weaker or negligible action of GFRAL signaling in inducing anxiety-like behavior (measured with the OFT and EPM behavioral paradigms) upon mitochondrial stress in female mice." (PMID 36271504, 2022). "Nevertheless, female mice do present a GFRAL-dependent induction of hypothalamic CRH, which has been often been linked to increased anxiety-like behaviors." (PMID 36271504, 2022). "This release influences feeding behavior and anxiety through GFRAL-dependent pathways." (PMID 40806735, 2025). "Moreover, the role of GFRAL in influencing anxiety-like behaviors indicates the possibility of targeting this pathway for new anxiety treatments." (PMID 40806735, 2025). "Finally, we identify that GFRAL signaling governs an anxiety-like behavior in male mice with muscle mitochondrial dysfunction, with females showing a less robust GFRAL-dependent anxiety-like phenotype." (PMID 36271504, 2022). "Finally, our data indicate a weak involvement of GFRAL signaling in inducing anxiety-like behavior assessed by OFT and EPM in female mice." (PMID 36271504, 2022). "Mice without GFRAL have normal HPA axis activation when faced with restraint stress or adrenaline but do not show typical anxiety-like behaviors." (PMID 40806735, 2025). "Here, we provide first experimental evidence for a direct link between mitochondrial dysfunction in a peripheral (non-brain) tissue with anxiety-like behavior, potentially via hypothalamic CRH signaling in a GFRAL-dependent manner." (PMID 36271504, 2022).
hepatic carcinoma (2 papers, 2020 to 2025). "The results showed that GFRAL protein was markedly upregulated in hepatic carcinoma, cholangiocarcinoma and colorectal carcinoma but was nearly undetectable in renal clear cell carcinoma." (PMID 33201838, 2020). "Additionally, in order to explore whether GFRAL expression was universal in other kinds of human cancers, we detected GFRAL expression in other types of tumors, such as hepatic carcinoma, cholangiocarcinoma, colorectal carcinoma and renal clear cell carcinoma." (PMID 33201838, 2020).
lung carcinoma (2 papers, 2024 to 2025). "In Europeans, associations were consistent with East Asians for GDF15, GFRAL, and lung cancer." (PMID 40527012, 2025).
type 2 diabetes (2 papers, 2017 to 2020). "In summary, we identified a novel metabolite locus (MOGAT2) in single variant analyses and four genes (GFRAL, BIN1, TFRC, OR51Q1) within gene-based tests and could show that two previously known mGWAS loci (FADS1 and REV3L) might be relevant for the risk of type 2 diabetes." (PMID 28729637, 2017).
energy metabolic disorder (1 paper, 2020). "They described that the GDF-15/GFRAL pathway regulates appetite and could be involved with energy metabolic disorder." (PMID 32847145, 2020).
gastric tumors (1 paper, 2021). "According to our data, the GFRAL expression was found to be significantly higher in gastric tumors compared with normal gastric mucosa, pointing out the role of this protein in the GC pathology." (PMID 34149933, 2021). "However neither GRFAL expression nor especially the joint expression of GDF15, GFRAL and RET have been evaluated in gastric tumors, in the context of the potential implication of the body-weight signaling pathway in GC pathogenesis." (PMID 34149933, 2021).
glioblastoma (1 paper, 2021). The most malignant astrocytic tumor (WHO grade IV). "Thus, it represents a potential therapeutic target in glioblastoma treatment by siRNA targeting GDF15 or its cognate receptor GFRAL (the GDNF family receptor alpha like)." (PMID 34532286, 2021).
malaise (1 paper, 2023). A feeling of general discomfort or uneasiness, an out-of-sorts feeling. "As a first step in this direction,we developed a peptide antagonist(GRASP) that blocks signaling at GFRAL and thus attenuates GDF15-and chemotherapy-induced malaise." (PMID 37506293, 2023).
metastatic disease (1 paper, 2025). "Therefore, GDF-15 or GFRAL inhibitors should be evaluated in patients with non-metastatic disease to improve their prognosis." (PMID 41294666, 2025).
thrombotic disease (1 paper, 2023). The formation of a blood clot in the lumen of a vessel or heart chamber; causes include coagulation disorders and vascular endothelial injury. "Thus, the GDF-15/GFRAL signaling pathway can possibly be considered a novel therapeutic target for thrombotic diseases." (PMID 38254638, 2023).
Ureteral obstruction (1 paper, 2026). Obstruction of the flow of urine through the ureter. "Western blot analysis further confirmed that GDF15 and GFRAL expression levels progressively decreased with prolonged ureteral obstruction." (PMID 41474228, 2026).
ventricular dilatation (1 paper, 2025). "In vivo, studies using GDF-15 analogs and antibodies against GFRAL to affect metabolic parameters and ventricular dilatation have shown potential for GDF-15-based therapeutic interventions." (PMID 39781722, 2025).
cancer (44 papers, 2018 to 2026). A tumor composed of atypical neoplastic, often pleomorphic cells that invade other tissues. "Stress-responsive cytokine GDF15 and its receptor GDNF receptor alpha like (GFRAL) have been implicated in cancer cachexia." (PMID 35994202, 2022). "This work demonstrates that, in combination with GDF15 anorectic effects during cancer cachexia, inhibition of brainstem activation of GFRAL by GDF15 mitigated cancer cachexia-associated wasting through dampening activation of the sympathetic nervous system." (PMID 34439145, 2021). "Elevated circulating GDF15 levels are often observed in pathological states such as cancer, cardiovascular disease, and metabolic disorders, where it acts as an anorexigenic signal via its receptor GFRAL in the hindbrain to suppress appetite." (PMID 41596279, 2026). "GDF15 triggers the activity through its receptor Glial-derived neurotrophic factor-family receptor α-like (GFRAL) and mediates multiple downstream signaling cascades, which are involved in the progression of cancers." (PMID 40128491, 2025). "Preclinical studies highlight the critical role of the GDF-15/GFRAL pathway in cancer cachexia, with its inhibition mitigating symptoms." (PMID 41294666, 2025). "In a mouse cancer cachexia model, treatment with an anti-GFRAL antibody improves metabolic conditions." (PMID 41294666, 2025). "Together, these data show that MAGEA-GDF15 mediated tumor-stromal crosstalk can promote Gem resistance and cancer progression in three different mouse models of PDAC probably by up-regulating GFRAL mediated AKT and ERK1/2 dependent cell survival pathway." (PMID 37814317, 2023). "Pro-tumorogenic effects of GDF15 have been linked with increased activity of different signaling pathways (PI3K/AKT, MAPK/ERK, TGF-β/SMAD), but apart from mediating cancer-induced cachexia, a role for GDF15/GFRAL axis in cancer remains to be determined." (PMID 35694408, 2022). "The anti-GFRAL antibody NGM120 is now under investigation in a Phase Ia/Ib clinical trial for the treatment of cancer and cancer anorexia-cachexia syndrome." (PMID 36078078, 2022). "With increasing evidence verifying the expression of GFRAL is also in cancer tissues, clues of GFRAL-independent effects of GDF-15 are also accumulating." (PMID 35963873, 2022). "A study of the effect of GDF-15 through glial cell-derived neurotrophic factor (GDNF) family receptor α-like protein (GFRAL) demonstrated that increased GDF-15 is related to the anorexia/cachexia observed in advanced cancer patients." (PMID 36008442, 2022). "A therapeutic antagonistic monoclonal antibody, which targets GFRAL and inhibits RET signaling by preventing the GDF15-driven interaction of RET with GFRAL on the cell surface, successfully prevented cancer cachexia." (PMID 35379793, 2022). "Blockade of a GDF15/GFRAL/RET interaction with the monoclonal antibody 3P10 resulted in a reversal of cancer cachexia in mouse models." (PMID 35743911, 2022). "Elevation in circulating GDF15 correlates with cancer cachexia and GDF15-induced weight loss in mice was reported to be mainly mediated by a GDNF family receptor alpha like (GFRAL)-Ret proto-oncogene (RET) signaling complex in brainstem neurons." (PMID 35379793, 2022). "GDF15 has been linked to cancer cachexia and a recent study found that inhibition of the GDF15-GFRAL activity by a GFRAL targeting antibody reversed cancer cachexia in mice." (PMID 33464381, 2021). "Despite the breakthrough in inhibiting the GDF15/GFRAL pathway for the treatment of cachexia in the mouse model, several issues concerning interplay between host and tumor must be addressed for cachectic cancer patients." (PMID 33442410, 2021). "GDF15 has been linked to cancer cachexia and inhibition of GDF15–GFRAL activity by a GFRAL targeting antibody reversed cancer cachexia in mice." (PMID 34831213, 2021). "The anorectic action of the cancer therapeutic drug, cisplatin, is blocked by inhibition of signalling through GFRAL." (PMID 32723474, 2020).